LAMA3 (laminin subunit alpha 3)
Diseases named in the same sentence as LAMA3 in open-access papers (continued):
Sharing a sentence is not in itself a finding about the gene and the disease.
cancer (44 papers, 2006 to 2025). A tumor composed of atypical neoplastic, often pleomorphic cells that invade other tissues. "Future studies, equipped with isoform-specific expression data, are warranted to dissect the contributions of each LAMA3 splice variant in cancer progression and prognosis." (PMID 38877482, 2024). "Previous studies have linked the LAMA3 gene to cancer aggressiveness, metastatic potential, and patient survival, while bioinformatics prescreening highlighted its unique expression patterns and prognostic relevance." (PMID 38877482, 2024). "In addition, high expression of other key genes like PAK2, LAMB3 and LAMA3 is also associated with malignant tumors." (PMID 37694778, 2024). "For example, although anti-PD1 therapy is an effective cancer treatment, the overexpression or mutations of LAMA3, CXCR2, and JAK1/2 could prevent the immune system from boosting effective antitumor immunity." (PMID 34660300, 2021). "Interestingly, several cancer progression-associated pathways, such as interleukin signalling, cell–cell communication and microtubule cytoskeleton regulation were enriched, suggesting the importance of LAMA3 in CCA malignancy." (PMID 38114514, 2023). "Interestingly, several cancer progression-associated pathways, such as interleukin signalling, cell–cell communication and microtubule cytoskeleton regulation were also enriched, suggesting the importance of LAMA3 in CCA malignancy." (PMID 38114514, 2023). "Immunohistochemical staining was applied to detect the expression level of LAMA3 in cancer tissues, and paraneoplastic tissues were used as controls to compare the differences in the expression level of LAMA3." (PMID 41264049, 2025). "The results demonstrated that LAMA3 expression was significantly higher in carcinoma specimens than in the adjacent tissues (P < 0.001)." (PMID 38452390, 2024). "Using GEPIA2 analysis, we here revealed that LAMA3 was upregulated in various types of cancers such as colon, kidney, liver, pancreas and rectum, but downregulated in some cancers, viz." (PMID 38114514, 2023). "As an epigenetic inactivation gene, LAMA3 has been reported in various cancer development and chemoresistance studies." (PMID 34289901, 2021). "LAMA3 also provides instruction for making a subunit of a protein called laminin 332, promoting cell migration in cancer cells." (PMID 34366863, 2021). "In PC, the expression level of LAMA3 in carcinoma tissue is upregulated, and patients with high LAMA3 expression have poor outcomes." (PMID 34732125, 2021). "LAMA3 and LAMC2 encode for products that are essential parts of laminin-322 (formerly known as laminin-5), which is known to stimulate cell migration in cancers and is related with the prognosis of diseases." (PMID 31182680, 2019). "The results of this study showed that LAMA3 expression was significantly higher in cancer tissues compared with paracancerous tissues (P < 0.05), suggesting that LAMA3 may play an important role in PDAC progression." (PMID 41264049, 2025). "LIPH and LAMA3 exhibited relatively higher expression in cancer cells and neutrophils." (PMID 37745080, 2023). "Of all the datasets investigated, LAMA3, LAMA5, LAMB3 and LAMC2 were found to be commonly upregulated in cancer when compared to adjacent tissue samples as well as in CCA tissues and cell lines." (PMID 38114514, 2023). "Subunit gamma-1 (LAMC1) was downregulated in all four cancer types, while all other subunits showed lower expression levels in SCLC; LAMC2, LAMA5, LAMB2 in LCC; and LAMA5, LAMB2, LAMA3 in AC as well." (PMID 35681609, 2022).
cancer (continued). "LINC00628 has been reported to inhibit the malignant progression of cancer through different mechanisms, such as binding to EZH2 to regulate the p57 or H3K27me3 level, and interacting with the promoter of LAMA3 or VEGFA." (PMID 35350786, 2022). "On the other hand, the upregulated genes, such as GNG12, GNG4, WNT9A, EDNRB, FGF18, LAMA3, MMP2, etc., were found in pathways in cancer." (PMID 36239109, 2022). "The most frequent cMDT disrupting interactions in over 90% of samples of a cancer type were those from the genes USP46, WDR74, RPS19, BOLA2B, NDUFA9, and LAMA3." (PMID 32879328, 2020). "On the other hand, LAMA3 and LAMC2 were identified in the network analysis of the grade 2 carcinoma." (PMID 32640634, 2020). "Other non-significant cancer-associated genes with significant isoform switch expression include IFNAR1, SMAD3, and LAMA3." (PMID 38059347, 2024). "The overexpressed integrin α (ITGA) subfamily genes ITGA2 and ITGA3 are predicted to be involved in cancer-related pathways such as PI3K-Akt signaling pathway and FA interacting with ECM genes such as laminin (LAMB3, LAMA3, and LAMC2) and collagen (COL10A1, COL12A1)." (PMID 34262595, 2021). "Fifteen members of cancer pathways, including FOS, TGFα, FZD8, MMP1, laminin subunit gamma 2, PTGS2, laminin subunit beta 3, ITGA2, laminin subunit alpha 3, VEGFC, WNT2B, heat shock protein 90 beta family member 1, WNT5B, FGF5 and WNT3A, were up-regulated in the MC group." (PMID 30482199, 2018). "We also examined the expression of LAMA3 and LAMC2 in PTC cell lines because many studies revealed that these could play an important role in carcinogenesis of several cancers." (PMID 29426928, 2018). "LAMB3, along with LAMA1, LAMA3 and LAMC2, was enriched in pathways involved in cancer." (PMID 28904855, 2017). "For example, the “Cancer, Cellular Movement, Cellular Growth and Proliferation” network encompasses EGFR, FGFR2 and other key genes, such as AURKA, a cell cycle checkpoint mediator, and SPP1, LAMA3 and GJA1, which play a role in cell communication." (PMID 23383013, 2013). "The cancer genome atlas data suggest robust expression of several laminin-encoding genes in advanced stages of EOC, although the effect of their expression on overall survival is not clear with the exception of LAMA3." (PMID 34376568, 2021).
infection (5 papers, 2016 to 2024). The state of being infected such as from the introduction of a foreign agent such as serum, vaccine, antigenic substance or organism. "Whereas WIPF3 and LAMA3 that associated with pathogen infection and inflammatory diseases specifically presented in C2." (PMID 33738257, 2021).
LAMA3 also shares sentences with these, for which no sentence is quoted: melanoma (4 papers); head and neck squamous cell carcinoma (3); adenocarcinoma (2); diabetes (2); Herlitz type junctional epidermolysis bullosa (2); liver cancer (2); recessive dystrophic epidermolysis bullosa (2); rheumatoid arthritis (2); skin disorder (2); acute myeloid leukemia (1); adrenocortical carcinomas (1); adrenocortical tumors (1); amoebiasis (1); atopic dermatitis (1); bladder cancer (1); bladder urothelial cancer (1); brain cancer (1); cardiomyopathy (1); cervical carcinoma (1); Cirrhosis (1); colitis (1); colorectal cancer (1); Congenital muscular dystrophy type 1A (1); COVID-19 (1); diabetes retinopathy (1); ductal carcinomas (1); endometrial cancer (1); Fraser Syndrome 1 (1); gestational diabetes (1); hepatocellular carcinoma (1).
A further 21 diseases each share a sentence with LAMA3 in 1 paper.